KCNA2 (potassium voltage-gated channel subfamily A member 2)
Description:
Voltage-gated potassium channel that mediates transmembrane potassium transport in excitable membranes, primarily in the brain and the central nervous system, but also in the cardiovascular system. Prevents aberrant action potential firing and regulates neuronal output. Forms tetrameric potassium-selective channels through which potassium ions pass in accordance with their electrochemical gradient. The channel alternates between opened and closed conformations in response to the voltage difference across the membrane. Can form functional homotetrameric channels and heterotetrameric channels that contain variable proportions of KCNA1, KCNA2, KCNA4, KCNA5, KCNA6, KCNA7, and possibly other family members as well; channel properties depend on the type of alpha subunits that are part of the channel. Channel properties are modulated by cytoplasmic beta subunits that regulate the subcellular location of the alpha subunits and promote rapid inactivation of delayed rectifier potassium channels. In vivo, membranes probably contain a mixture of heteromeric potassium channel complexes, making it difficult to assign currents observed in intact tissues to any particular potassium channel family member. Homotetrameric KCNA2 forms a delayed-rectifier potassium channel that opens in response to membrane depolarization, followed by slow spontaneous channel closure. In contrast, a heteromultimer formed by KCNA2 and KCNA4 shows rapid inactivation. Regulates neuronal excitability and plays a role as pacemaker in the regulation of neuronal action potentials (By similarity). KCNA2-containing channels play a presynaptic role and prevent hyperexcitability and aberrant action potential firing (By similarity). Response to toxins that are selective for KCNA2-containing potassium channels suggests that in Purkinje cells, dendritic subthreshold KCNA2-containing potassium channels prevent random spontaneous calcium spikes, suppressing dendritic hyperexcitability without hindering the generation of somatic action potentials, and thereby play an important role in motor coordination (By similarity). Plays a role in the induction of long-term potentiation of neuron excitability in the CA3 layer of the hippocampus (By similarity). May function as down-stream effector for G protein-coupled receptors and inhibit GABAergic inputs to basolateral amygdala neurons (By similarity). May contribute to the regulation of neurotransmitter release, such as gamma-aminobutyric acid (GABA) (By similarity). Contributes to the regulation of the axonal release of the neurotransmitter dopamine (By similarity). Reduced KCNA2 expression plays a role in the perception of neuropathic pain after peripheral nerve injury, but not acute pain (By similarity). Plays a role in the regulation of the time spent in non-rapid eye movement (NREM) sleep (By similarity).
Synonyms: Kv1.2; HK4; DEE32; EIEE32; HBK5; HUKIV; MK2; NGK1; RBK2
Tractability: Small molecule: an approved drug acts on it; it belongs to a druggable protein family. Antibody: UniProt places it where antibodies can reach, with high confidence; its Gene Ontology location is reachable by antibodies, with high confidence; UniProt predicts a signal peptide or a membrane-spanning region. PROTAC: ubiquitination databases record sites on it; its protein half-life has been measured; a small molecule that binds it is known.
Target class: Potassium channels; Ion channel; Voltage-gated ion channel; Voltage-gated potassium channel
Gene: Protein-coding gene on chromosome 1 (110,519,837 to 110,631,474, reverse strand). Ensembl gene ENSG00000177301.
Subcellular location: Cell membrane; Membrane; Cell projection, axon; Synapse; Endoplasmic reticulum membrane; Cell projection, lamellipodium membrane; Synapse, synaptosome; Presynaptic cell membrane; Cell projection, dendrite; Cell junction, paranodal septate junction
Pathways (Reactome):
Neuronal System: Voltage gated Potassium channels
Gene Ontology:
Molecular function: protein binding; voltage-gated potassium channel activity; delayed rectifier potassium channel activity; potassium channel activity; kinesin binding; monoatomic ion channel activity; outward rectifier potassium channel activity; voltage-gated monoatomic ion channel activity involved in regulation of postsynaptic membrane potential; voltage-gated monoatomic ion channel activity involved in regulation of presynaptic membrane potential
Biological process: potassium ion transmembrane transport; action potential; neuronal action potential; potassium ion transport; regulation of dopamine secretion; sensory perception of pain; cerebral cortex development; corpus callosum development; monoatomic ion transport; optic nerve development; potassium ion export across plasma membrane; protein homooligomerization; regulation of circadian sleep/wake cycle, non-REM sleep; regulation of postsynaptic membrane potential; regulation of presynaptic membrane potential; transmembrane transport
Cellular component: plasma membrane; voltage-gated potassium channel complex; axon; axon terminus; dendrite; juxtaparanode region of axon; lamellipodium; membrane; neuronal cell body membrane; perikaryon; presynaptic membrane; axon initial segment; calyx of Held; endoplasmic reticulum membrane; glutamatergic synapse; lamellipodium membrane; paranodal junction; postsynaptic membrane; potassium channel complex; synapse
Genetic constraint (gnomAD): Loss-of-function variants: 11 observed, 33.92 expected, observed/expected ratio (o/e) 0.32, 90% interval 0.2 to 0.54. The upper end of that interval is the gene's LOEUF score, 0.54, which puts it in group 2 of 6, group 1 being the genes least tolerant of losing a copy. Missense variants: 291 observed, 653.11 expected, observed/expected ratio (o/e) 0.45, 90% interval 0.4 to 0.49. Synonymous variants: 222 observed, 244.62 expected, observed/expected ratio (o/e) 0.91, 90% interval 0.81 to 1.01.
Gene-disease validity (ClinGen):
ClinGen rates the evidence that KCNA2 causes each of these diseases.
genetic developmental and epileptic encephalopathy (autosomal dominant): Definitive. A complex neurodevelopmental disorder characterized by a range of developmental delays and epileptic encephalopathy phenotypes.
Homologues: Orthologues: macaque KCNA2 (99% identical), dog KCNA2 (99% identical), guinea pig KCNA2 (99% identical), pig KCNA2 (99% identical), mouse Kcna2 (99% identical), rat Kcna2 (99% identical), rabbit KCNA2 (99% identical), tropical clawed frog kcna2 (94% identical), zebrafish kcna2b (92% identical), zebrafish kcna2a (88% identical). Paralogues in human: KCNA1 (79% identical), KCNA3 (77% identical), KCNA4 (70% identical), KCNA6 (68% identical), KCNA5 (67% identical), KCNA10 (60% identical), KCNA7 (57% identical), KCNC3 (36% identical), KCNC4 (36% identical), KCNC2 (36% identical), KCND1 (35% identical), and 19 more.
Diseases named in the same sentence as KCNA2 in open-access papers:
KCNA2 is named in the same sentence as 101 diseases in open-access papers, as found by Europe PMC text mining. Sharing a sentence is not in itself a finding about the gene and the disease. The quoted sentences say what the papers report.
epilepsy (48 papers, 2015 to 2026). A brain disorder characterized by episodes of abnormally increased neuronal discharge resulting in transient episodes of sensory or motor neurological dysfunction, or psychic dysfunction. "Further, it has been reported that mutations and abnormal functions of KCNA2 in humans can lead to different neurological diseases that include epilepsy, autism spectrum disorder, pain, movement disorders, and temporal lobe epilepsy." (PMID 41155561, 2025). "Many genetic polymorphisms within KCNA2 have been extensively investigated, and several were correlated with epilepsy risk and have been reported in patients with BFNIS, GEFS+, and Dravet syndrome." (PMID 40142207, 2025). "At the corresponding positions in KCNA2, the de novo P405L and P407A mutations have been associated with neurodevelopmental syndromes in which epilepsy, motor and cognitive delay co-exist." (PMID 35897654, 2022). "In 2015, pathogenic de novo variants in KCNA2 were first described in six individuals with early-onset severe epilepsy, cognitive impairment, and ataxia." (PMID 33802230, 2021). "Inherited and de novo variants in KCNA2 have been associated with a spectrum of symptoms ranging from remittent epilepsy to epileptic encephalopathy, development delay, and ataxia." (PMID 34576077, 2021). "Here we describe a novel variant in the KCNA2 gene, the E236K in the S2 segment of the protein, associated with early onset epilepsy and cerebellar ataxia, and test the effect of 4-AP on mutant channels." (PMID 34576077, 2021). "The cellular mechanisms underlying epilepsy and ataxia following either LoF or GoF variants in KCNA2 are still unclear." (PMID 34576077, 2021). "In vitro functional studies provided valuable information to link Kv1.2 variants to the occurrence of ataxia and epilepsy in humans and provide evidence for a significant genotype-phenotype correlation in KCNA2-encephalopathy." (PMID 34576077, 2021). "Of note, loss and gain of function mutations, including a de novo P405L mutation, in KCNA2 genes have been associated with severe neurodevelopmental syndromes in which epilepsy and motor and cognitive delay co-exist." (PMID 32331416, 2020). "KCNA2 mutations associate with two types of phenotypes based on the severity of the encephalopathy and of the seizure disorder." (PMID 29976148, 2018). "We also emphasize the finding of a mutation in KCNA2 in a patient with early onset epilepsy and ataxia." (PMID 29389947, 2018). "A striking example is provided by family PKMR82, in which a homozygous nonsense mutation (p.Arg65*) in KCNA2 was associated with mild to moderate ID, speech delay, strabismus, walking delay and epilepsy." (PMID 27457812, 2017). "Moreover, complete loss-of-function (LOF) in the p.H310R variant in KCNA2 results in epilepsy, while a gain-of-function (GOF) p.H310Y variant was found to be involved in developmental delay in children." (PMID 41155561, 2025). "KCNA1 (Kv1.1) and KCNA2 (Kv1.2) have been associated with epilepsy." (PMID 39253727, 2024). "In this work, we report on a KCNA2 variant discovered in a male child with epilepsy." (PMID 35439054, 2022). "We report on a heterozygous KCNA2 variant in a child with epilepsy." (PMID 35439054, 2022). "Deletion of Kcna1/Kv1.1 or Kcna2/Kv1.2 has been reported to cause epilepsy in rodents." (PMID 36668838, 2022). "As said, the mechanisms underlying epilepsy and ataxia due to KCNA2 GoF variants are still unknown, thus mere hypotheses can be drawn to explain the clinical potential of 4-AP." (PMID 34576077, 2021). "In addition, Imbrici found that the E236K variant in KCNA2 exhibited voltage-dependent activation, shifting toward negative potentials and slower kinetics of deactivation and activation, causing early onset of epilepsy." (PMID 37483435, 2023).
epilepsy (continued). "The clinical usefulness of this potassium channel blocker may be hampered by its proconvulsant activity and cardiac safety issues at higher doses, thus the benefit/risk profile of 4-AP in KCNA2 epilepsy should be carefully investigated and eventually new derivatives developed." (PMID 34576077, 2021). "Based on the severity of the encephalopathy and the seizure disorder, the phenotype associated with the KCNA2 variant might be differentiated into two main groups, with the milder phenotype correlating with loss-of-function variants and more severe phenotype with gain-of-function variants." (PMID 33897753, 2021). "First, we studied KCNA/Kv1, Kcna1, Kcna2, Kcna3, Kcna4, Kcna5, and Kcna6 because of their involvement in neuronal excitability, epilepsy, and other neurological disorders." (PMID 41155561, 2025). "The levels of Vitamin D and Vitamin B12 levels among epilepsy patients were influenced by KCNA2 and KCNAB1, respectively." (PMID 40142207, 2025). "The genetic underpinnings of epilepsy have helped in the classification of these syndromes, and examples now include rare monogenic forms involving KCNA2, KCNT1, and SCN1A." (PMID 40871704, 2025). "Regarding the etiology of epilepsy, five (11.1%) were genetic, including one with SCN2A mutation, one with KCNA2 mutation, one with MBD5 mutation, one with WFS1 mutation, and one with OCRL mutation." (PMID 38419715, 2024). "Pathogenic variants in CACNA1A, KCNA2 and KMT2B were associated with epilepsy; seizures are a known feature of the first two." (PMID 39048885, 2024). "For example, EA and epilepsy associations include EA1 (KCNA1), EA2 (CACNA1A), EA5 (CACNB4), EA6 (SLC1A3), SCN2A, KCNA2, ATP1A3, SLC2A1, and PRRT2." (PMID 37008993, 2023). "Variants in genes encoding potassium channels induce different forms of epilepsy, ranging from benign familial neonatal seizures (KCNQ2/3, encoding KV7.2/3) to severe developmental and epileptic encephalopathies (KCNA2, encoding KV1.2)." (PMID 37360341, 2023). "We identified four key potassium channel genes, KCNA1, KCNA2, KCNJ11, and KCNS1, that are associated with the pathogenesis of epilepsy." (PMID 37483435, 2023). "Genetic variants in both KCNA1 and KCNA2, which disrupt the proline residues of the PVP motif, have been identified in children with severe epilepsy and comorbidities (P403S and P405S/L in Kv1.1 and P405L and P407A in Kv1.2)." (PMID 35897654, 2022). "A child with epilepsy has a previously unreported, heterozygous mutation in KCNA2, the gene encoding KV1.2 proteins." (PMID 35439054, 2022). "In these disorders and epilepsies, carriers of whole-gene deletions are less severely affected than carriers of single point mutations (e. g., in SCN2A, KCNT1, KCNA2, SPTAN1)." (PMID 38835873, 2022). "The first group is the studies that described the generation of patient-specific iPSC lines that carry genetic variants in genes associated with epilepsy, such as SCN1A, GNB5, LGI1, GRIN2A, KCNC1, or KCNA2." (PMID 36552721, 2022). "The clinical phenotype with self-limiting infantile-onset seizures in this boy is partially overlapping with the mild end of KCNA2-related epilepsy." (PMID 33802230, 2021). "Based on these findings, the repurposing of riluzole (a sodium channel and NMDA receptor blocker and BK channel activator), is suggested as a treatment for epilepsy caused by LGI1, KCNA1 or KCNA2 mutations." (PMID 32331416, 2020). "This study aims to investigate the effects of the three potassium channel genes KCNA1, KCNA2, and KCNV2 on increased susceptibility to epilepsy as well as on responsiveness to antiepileptic drugs (AEDs)." (PMID 30441785, 2018).
epilepsy (continued). "Microdeletions found only in GGE patients harboured a high proportion of genes previously associated with epilepsy and neuropsychiatric disorders (NRXN1, RBFOX1, PCDH7, KCNA2, EPM2A, RORB, PLCB1)." (PMID 25950944, 2015). "We identified a novel variant in KCNA2, E236K, in a Serbian proband with non-progressive congenital ataxia and early onset epilepsy, treated with sodium valproate." (PMID 34576077, 2021). "Interestingly, Kcna2-null mice, which lack Kv1.2 subunits, also exhibit epilepsy and premature death phenotypes, but they appear more severely than in Kcna1-null mice." (PMID 32316562, 2020). "These microdeletions affected 158 protein-coding RefSeq genes and exhibited an enrichment of genes previously associated with epilepsy (NRXN1, RBFOX1, PCDH7, KCNA2, EPM2A, RORB, PLCB1) and neuropsychiatric disorders (DPYD, CADM2, PARK2, GRM8, TSNARE1, TPH2, MACROD2)." (PMID 25950944, 2015). "Previous research has shown that three of the four key potassium channel genes (KCNA1, KCNA2, KCNJ11, and KCNS1) play vital roles in seizures and epilepsy." (PMID 37483435, 2023). "In this study, blood samples were collected from 299 healthy controls and 296 Jordanian Arab patients with epilepsy (consisting of 162 patients with good response and 134 patients with poor response), and seven KCNA1, KCNA2, and KCNV2 SNPs." (PMID 30441785, 2018). "We direct our attention to the possible influence of the KCNA1, KCNA2, and KCNV2 genes on the pathogenesis of epilepsy and responsiveness to treatment involving common drugs." (PMID 30441785, 2018). "The two modules had the proteins, such as KCNA2, GABRA1, and GRIN2A, which had been recently be discovered as novel epilepsy genes." (PMID 28388656, 2017). "However, the effects of the KCNA1, KCNA2, and KCNV2 genes on epilepsy development and the effectiveness of AEDs are not yet clear." (PMID 30441785, 2018).
Epileptic encephalopathy (24 papers, 2015 to 2025). A condition in which epileptiform abnormalities are believed to contribute to the progressive disturbance in cerebral function. "De novo mutations in KCNA2 are associated with epileptic encephalopathy, with about half of the patients with KCNA2 mutations showing symptoms of ataxia and atrophy of the cerebellum." (PMID 37374132, 2023). "Uysal reported that patients with mutations in KCNA2 showed early onset developmental and epileptic encephalopathies." (PMID 37483435, 2023). "Some mutations in the KCNA2 gene result in gain-of-function of the channel activity and lead to several channelopathies including epileptic encephalopathies early infantile epileptic encephalopathy, and myoclonus epilepsy." (PMID 37624263, 2023). "Recently, de novo and inherited heterozygous variants in KCNA2 gene have been identified in patients presenting with early infantile epileptic encephalopathy, intellectual disability, delayed speech, development delay and ataxia." (PMID 34576077, 2021). "Recently, heterozygous mutations in KCNA2 have been associated with a spectrum of symptoms extending from epileptic encephalopathy, intellectual disability, and cerebellar ataxia." (PMID 34576077, 2021). "The KCNA2 gene encodes the voltage-gated K+ channel Kv1.2, and the mutations in it can cause progressive myoclonus epilepsy and epileptic encephalopathy." (PMID 32655475, 2020). "KCNA2 gene mutations were described to cause a new molecular entity within the developmental and epileptic or epileptic encephalopathies." (PMID 32903602, 2020). "Mutations in KCNA2 were recently recognized as the cause of epileptic encephalopathies and early onset ataxia." (PMID 29389947, 2018). "Recently, de novo KCNA2 missense mutations were associated with epileptic encephalopathy, ataxia, variable ID55, 56 and other features reminiscent of those found in family PKMR82." (PMID 27457812, 2017). "Investigators from the University Leipzig and University of Tübingen report mutations of KCNA2 as a novel cause of epileptic encephalopathy." (PMID 26933568, 2015). "De novo loss- or gain-of-function mutations in KCNA2 have been identified to cause human epileptic encephalopathy." (PMID 25950944, 2015). "Currently, de novo mutations of KCNA2 gene, have been confirmed to cause a new molecular entity within the epileptic encephalopathies, which could cause either a dominant-negative loss-of-function or a gain-of-function of the voltage-gated K+ channel KCNA255." (PMID 39019913, 2024). "Interestingly, both loss-of-function and gain-of-function mutations of the Kv1.2-encoding gene, KCNA2, were associated with epileptic encephalopathy." (PMID 32269520, 2020).